IL6 (interleukin 6)
Diseases named in the same sentence as IL6 in open-access papers (continued):
Sharing a sentence is not in itself a finding about the gene and the disease.
Infertility (91 papers, 2009 to 2026). "Elevated levels of IL-6 have been associated with disruptions in spermatogenesis, potentially contributing to infertility." (PMID 39968364, 2024). "For example, both elevated and reduced IL-6 concentrations have been associated with an increased risk of infertility and miscarriage." (PMID 39578791, 2024). "Leukocytospermia is an established marker of inflammation and it has been associated with increased semen levels of interleukin-6 and tumor necrosis factor-α, both inflammatory cytokines, in infertile patients." (PMID 33226627, 2021). "IL-6 is produced in abundance by the myometrium, cervix, and choriodecidua before and during labor, and elevated or deficient IL-6 levels are associated with infertility, fetal loss, and other pregnancy disorders." (PMID 34490133, 2021). "Concerning the role of IL6 in estrogen metabolism, there is emerging evidence linking IL6 deficiency with reproductive impairment, leading to in how this cytokine contributes to infertility." (PMID 29182577, 2017). "For instance, high levels of IL-6 and IL-8 promote the peroxidation process, affecting the function of sperm and causing infertility during inflammation of the male genital tract." (PMID 27364628, 2016). "High levels of IL-6 levels have been previously reported to be present in the tubal fluids of patients with infertility caused by chlamydial infections." (PMID 19397832, 2009). "The decrease in AMH pretreatment might be caused by chronic inflammation and increased levels of cytokines, especially IL-6, which have been shown to be associated with the occurrence of EM-associated infertility." (PMID 38562412, 2024). "Local inflammation, caused by disordered vaginal microbiota, may lead to reduced levels of fertility; higher levels of cervical interleukin (IL)-1b, IL-6, and IL-8 cytokines have been reported to be associated with infertility." (PMID 35909180, 2022). "As the key proinflammatory cytokine, high expression of IL-6 can induce fibroblast proliferation, aggravate local pelvic adhesion and tubal injury, and eventually cause local tubal tissue adhesion, stenosis, and quince, leading to infertility." (PMID 34754312, 2021). "Moreover, exploring additional polymorphisms in IL-6 gene and other inflammatory genes in fertile and infertile men could contribute to obtaining more precise conclusions." (PMID 39968364, 2024). "Concurrently, pro-inflammatory mediators like interleukin-6 (IL-6), interleukin-8 (IL-8), and tumor necrosis factor-alpha (TNF-α) are frequently found in the seminal plasma of infertile men and are linked to poor semen parameters and testicular dysfunction." (PMID 41750676, 2026). "Higher cervical concentrations of the cytokines interleukin (IL)-1β, IL-6, and IL-8 have been observed in women with infertility and BV." (PMID 40652342, 2025). "Higher IL-6 levels in infertile women receiving assisted reproductive technology (ART) were connected to a lower chance of implantation and pregnancy in some studies." (PMID 40726888, 2025). "For example, the serum copper (Cu) level correlated positively with interleukin 6 (IL-6) in women undergoing infertility treatment, and with interleukin 8 (IL-8) in a prospective birth cohort study." (PMID 41226467, 2025). "Numerous studies have reported elevated concentrations of inflammatory factors, such as tumor necrosis factor-a (TNF-a), and interleukin 6 (IL-6), in the serum and FF of infertile women with PCOS58,59." (PMID 38486041, 2024). "A Danish study of 2140 patients found that interleukin-6 (IL-6) concentrations were significantly higher among men with male factor infertility compared with the controls." (PMID 37892037, 2023). "Pro-inflammatory cytokine IL-1β was significantly dysregulated while TNF-α and IL-6 were noticeably increased in infertile males, considering the possibility of cholinergic-mediated systemic inflammation in male infertility." (PMID 37027384, 2023).
Infertility (continued). "Many studies report elevated IL6 in SP from infertile men compared to fertile men5, 6, 52, 77, 78, 79, 80, 81, 82 and negative correlations between IL6 and sperm quality parameters." (PMID 36891953, 2023). "Here we demonstrated the changes of the IL-6 gene expression in the endometrium of infertile and fertile women." (PMID 37576599, 2023). "Previous studies have shown that the concentrations of TNFα and IL-6 were higher in the blood and follicular fluid of infertile women with PCOS than in the control group." (PMID 35928256, 2022). "Endometrial levels of IL-6 peak at the time of implantation and are decreased in women with infertility and recurrent miscarriage." (PMID 35813634, 2022). "The impact of both combined C. trachomatis and M. genitalium on seminal inflammatory parameters (concentration of neutrophils, seminal IL-6) also remained significant in the selected infertility group patients." (PMID 34948264, 2021). "The molecules most involved in infertility are interleukin (IL) -1, IL-2, IL-6, IL-8, interferon-ɣ, and tumor necrosis factor-α (TNF-α)." (PMID 33925640, 2021). "In this sense, recent meta-analyses support the association between elevated serum IL-6 and/or IL-8 concentrations and the occurrence of EMS-associated infertility." (PMID 34829910, 2021). "As previously reported, the serum levels of TNF-α and IL-6 were higher in the secondary infertility group compared to the uterine fibroids group." (PMID 33092547, 2020). "Existing evidence has implicated that cytokines including IL-6 can modulate and influence sperm activity and male fertility, as the IL-6 concentration in seminal plasma of infertile men was found to be significantly higher than that of fertile men26." (PMID 31664153, 2019). "Significantly, we demonstrated for the first time that heterozygous deletion of Il-6, partially rescued male mouse infertility phenotype through improving sperm morphology and increasing the sperm motility and progression." (PMID 31664153, 2019). "For example, PBMCs from Chlamydia-positive infertile women secreted more IL-6, IL-10 and IL-1β in response to Inc proteins than PBMCs from Chlamydia-positive fertile women." (PMID 24238294, 2013). "IL-6 has been correlated with ROS in infertile males with varicocele and has been shown to contribute to male infertility." (PMID 22536401, 2012). "In contrast, IL-1β, IL-4, IL-5, IL-6, IL-10 mRNA expression levels were significantly higher (P < 0.05) in cells obtained from CT-positive infertile women compared to controls and CT-positive fertile women." (PMID 19698128, 2009). "The levels of IFN-a, TNF and NOS2 were similar for fertile and infertile animals during Period 1, although IL6 tended to be higher in infertile animals (P = 0.06)." (PMID 19476661, 2009). "In another report, high IL-6 levels have been found to be secreted from CT EB-stimulated cervical cells obtained from CT-positive infertile women." (PMID 19397832, 2009). "Additionally, chronic low-grade inflammation increases pro-inflammatory cytokines like TNF-α and IL-6, which can damage the uterine microenvironment and impair ovarian function, contributing to infertility." (PMID 39815248, 2025). "These DEGs were intricately linked to IL6 signaling, autophagy markers (LC3), ubiquitination pathways, and miRNA interactions, revealing a complex regulatory network that underscores the multifactorial nature of infertility." (PMID 41227338, 2025). "The gene expression analysis revealed significant changes in the endometrium regarding the genes associated with cell death (BAK1), epigenetic DNA modification (TET2) and the immune response (IL-6) which were upregulated in females with the diagnosed unexplained infertility." (PMID 37576599, 2023). "For example, some pro-inflammatory cytokines (IL-6, IL-8) are related to inflammation, which may be responsible not only for failed IVF, but also could be associated with unexplained infertility." (PMID 37576599, 2023).
Infertility (continued). "Indeed, FF levels of TNF-α and IL-6 were found to be higher in infertile women with PCOS compared to control women." (PMID 37493841, 2023). "Animal and human studies suggested that excess intereluken-6 (IL-6) could suppress reproductive function and lead to unexplained infertility." (PMID 35721737, 2022). "It was suggested that IL-6 may participate and promote different pathophysiologies, such as testicular cancer, inflammation and infertility." (PMID 35409373, 2022). "We assessed the potential role of proinflammatory cytokines (TNF-α, IL-6 and IL-1α) and microRNAs (miR-146a-5p, miR-34a-5p and miR-23a-3p) in the seminal plasma of infertile men compared to controls, evaluating their correlation with seminal and biochemical parameters." (PMID 34319544, 2021). "The association between IL-6 cytokine levels and semen quality is still debated, on one hand, elevated levels of IL-6 have been documented in infertile men with oligo-astheno-teratozoospermia, on the other hand, there is no linkage between cytokine levels and sperm quality." (PMID 34319544, 2021). "Elevated levels of the pro-inflammatory cytokine IL-6 and oxidative stress may play a pivotal role in the pathophysiology of infertility." (PMID 34198509, 2021). "Similarly, the level of IL-6, another marker of inflammation, was found to be elevated in the seminal plasma of infertile males." (PMID 33714944, 2021). "Chronic inflammation is considered another theory for infertility; the mediating cell being local macrophages, which, producing pro-inflammatory and chemotactic cytokines such as IL-6, IL-10, HIF-alpha, VEGF, catalase, among others, would impair implantation, disfavoring fertility." (PMID 33656838, 2021). "Furthermore, heterozygous deletion of Il-6 gene in Ncoa5+/− male mice partially improved spermatozoa motility and moderately rescued infertility phenotype." (PMID 31664153, 2019). "Furthermore, infertile heifers had significantly higher expression of TNFα, IL-6, and CXCL5 in their white blood cells." (PMID 30181662, 2018). "In infertile patients with varicoceles, increased levels of IL-6 and ROS might reduce the total antioxidant capacity." (PMID 27364628, 2016). "In addition, patients with Chlamydia-induced salpingitis and upper reproductive tract inflammation which are established etiologies of infertility, demonstrated higher IL-6 levels in the infiltrating lymphocytes in the acute phase of the disease." (PMID 22536401, 2012). "IL-6, generated in the process of oxidative stress, not only regulates the inflammatory milieu and assists in maintenance of chronic inflammatory state but also directly affects the metaphase-II oocyte spindle and contributes to infertility." (PMID 22536401, 2012). "Interleukin-6 (IL-6) is a pleotropic cytokine which is known to activate acute phase proteins and maintain chronic inflammatory states ranging from cardiovascular diseases to infertility." (PMID 22536401, 2012). "Overall our data shows that CT IncB and IncC are able to upregulate expression of cytokines, namely interferon-gamma, IL-12, IL-23 and GM-CSF in CT-positive fertile women while expression of IL-1 Beta, IL-4, IL-5, IL-6 and IL-10 were upregulated in CT-positive infertile women." (PMID 19698128, 2009). "Significant higher expression (P < 0.05) of Interferon-gamma, IL-12, IL-23 and GM-CSF were found in Inc-stimulated CD4 enriched cervical cells of CT-positive fertile women and contrastingly high IL-1 Beta, IL-4, IL-5, IL-6 and IL-10 levels were found in CT-positive infertile women." (PMID 19698128, 2009). "Consequently, IL-6 is crucial in the pathophysiology of infertility and gestational disorders." (PMID 39202588, 2024). "Moreover, we have also demonstrated that ISO-induced oxidative stress generates inflammation via the upregulation of MPO, TNF-α, and IL-6, which should also contribute to the reduction in testosterone concentrations and the reduced ratio of mature sperm, leading to infertility." (PMID 35326087, 2022).
Infertility (continued). "Elevation of IL-6 in unexplained infertile women may lead to PTB through inflammatory pathways." (PMID 35721737, 2022). "Moreover, infertile patients with varicocele exhibited an elevated levels of IL-6." (PMID 31926565, 2020). "If there is a connection between systemic inflammation and infertility, the IL6 pathway or pathways for other cytokines (NK cells) could be an experimental target for treatment, possibly forming the basis for a successful treatment for all patients with inflammatory diseases and fertility problems." (PMID 25101180, 2014). "Screening via the STRING platform and Cytoscape 3.10.1 software yielded four core targets for ATBC-induced infertility-HSP90AA1, PIK3CA, CASP3, HRAS-and four core targets for icariin treatment-IL6, TNF, STAT3, and INS." (PMID 41898778, 2026). "This suggests a feedback loop where IL6-induced inflammation upregulates ICAM1, while miR-146a-5p acts as a compensatory brake, a mechanism likely disrupted in infertility." (PMID 41227338, 2025). "A study explained that IL-6 poses adverse effects and is higher in PCOS women with infertility than in healthy controls." (PMID 36677054, 2023). "Inflammation is a crucial factor in male infertility, and higher seminal plasma concentrations of IL-1, IL-6, interferon-γ, and TNF-α have been found in infertile patients compared to normal controls." (PMID 38077946, 2023). "In summary, in fertile and infertile patients’s seminal plasma, the expression of cytokines (TNF-α, IL-6), miRNAs (miR-146a-5p, miR-34a-5p, miR-23a-3p) and IL-1α protein was not strongly correlated to any standard sperm parameters." (PMID 34319544, 2021). "It has been reported that the levels of IL-2, IL-6, IL-10 and TGFB1 in seminal plasma or serum are significantly elevated in infertility patients compared to healthy controls." (PMID 31855573, 2019). "Aside from this, cytokines such as IL-1, IL-6, and tumor necrosis factor (TNF) can lessen sperm motility and decrease the likelihood of sperm reaching the ovum, further contributing to infertility in males." (PMID 28515223, 2017). "It has beenfound that concentrations of interleukins such asIL-1, IL-6 and TNF were significantly increasedin semen of infertile patients." (PMID 28868836, 2017). "Between Period 1 and 2, there was a decrease in the level of expression of IL6 (P < 0.05) and NOS2 (P < 0.05) in infertile animals and NOS2 (P < 0.05) for fertile animals." (PMID 19476661, 2009). "Significantly higher levels of IL-1β, IL-6 and IL-10 were secreted from IncB or IncC stimulated CD4+ T cells obtained from CT-positive infertile women as compared to CT-positive fertile women or controls (P < 0.05)." (PMID 19698128, 2009). "In this study we detected high levels of IL-1β, IL-6, IL-4, IL-5 and IL-10 in IncB or IncC-stimulated CD4+ T cells in CT-positive infertile women compared to CT-positive fertile women and controls." (PMID 19698128, 2009). "Significantly high levels of TNF-α and IL-6 levels were secreted in CD4+ T cells from CT-positive fertile and infertile women compared to controls." (PMID 19698128, 2009). "In men, higher levels of IL-1, IL-6, and TNF were detected in those with infertility." (PMID 40933264, 2025). "Cytokines like interleukin 1β (IL-1β), IL-6, IL-10, IL-18, tumor necrosis factor α (TNF-α), interferon g (IFN-g), and transforming growth factor β1 (TGF-β1) are notably elevated in idiopathically infertile males and those with varicocele." (PMID 40070583, 2025). "The PDE4 inhibitor rolipram and the different pathways such as IL-6/NF-κB/TNFα/MAPK and cAMP/AQP5 mediating its effects against ovarian torsion damage may be a promising target for ovarian damage or infertility." (PMID 38453769, 2024).
Infertility (continued). "In addition, some pro-inflammatory cytokines, such as IL-6, and anti-inflammatory cytokines have been reported to be associated with various gynecological conditions, i.e., polycystic ovary syndrome (PCOS), tubal factor infertility, or infertility of unknown origin." (PMID 37108732, 2023). "The activation of IL‐6/JAK2/STAT1 and STAT3 signaling pathways are found in the hydrosalpinx in infertile patients, indicating that they might be involved in the pathogenesis of hydrosalpinx." (PMID 37382258, 2023). "Despite the existing controversy regarding the role of cytokines in fertility, our results were in agreement with previously published data reporting that significantly elevated IL-6 levels were found in infertile patients and revealed an apparent negative correlation with sperm number." (PMID 31926565, 2020). "Moreover, infertile patients with leukocytospermia or varicocele showed significantly reduced seminal concentrations of obestatin and ghrelin concomitant with increased levels of CAT, MDA, IL-6, and TNF-α with respect to those observed in the control group." (PMID 31781347, 2019). "IL-6 and TNF-α were higher in the infertile group but they were not statistically significant." (PMID 37027384, 2023).